NLRP3 (NLR family pyrin domain containing 3)
Diseases named in the same sentence as NLRP3 in open-access papers (continued):
Sharing a sentence is not in itself a finding about the gene and the disease.
cancer (continued). "However, there are newly available reports that have begun to provide some insight into NLRP3 regulation in cancers." (PMID 34638239, 2021). "Inflammasome NLRP3 downregulation inhibits cancer cell development and hinders CM metastasis." (PMID 34753832, 2021). "Recent research demonstrated that reduced NLRP3 inflammasome and IL-1β expression could inhibit the progression of cancer cells." (PMID 34747716, 2021). "Doxycycline was shown to regulate inflammation; however, its effect on NLRP3 in cancer remains largely unknown." (PMID 34577552, 2021). "Moreover, we will focus on current strategies for targeting the NLRP3 inflammasome, including a diverse range of agents, such as inhibitors, antagonists and monoclonal antibodies, which have potential for cancer treatment." (PMID 34064909, 2021). "In addition, melanoma NLRP3 contributes to the progression of malignant neoplasms in all stages, including tumor growth, proliferation, invasion, and metastasis, that also indicate the pathogenic role of inflammasomes in oncogenesis." (PMID 34885171, 2021). "To verify whether a deletion of NLRP3 in HCC actually induces effective NK-mediated cancer immune surveillance in vivo, we intravenously injected WT or NLRP3 KO SK-Hep1-Luc cells to NRG mice, restrained in lymphocytes (B, T, and NK cells)." (PMID 34502191, 2021). "The results demonstrate heterogeneous responses in the activation of genes of the NLRP3 inflammasome pathway in the adipose tissue of patients with cancer cachexia, rendering this pathway a potential target for therapy aiming at decreasing chronic inflammation in cancer." (PMID 34630405, 2021). "In addition to the NLRP3 inflammasome, other inflammasomes are involved in modulating immunity and several inflammation-related diseases, such as autoimmune diseases and cancer." (PMID 34522213, 2021). "It has been reported that microRNA22 could repress cancer cell growth by downregulating NLRP3 in our and other previous studies." (PMID 34454534, 2021). "Activation of NLRP3 inflammasome enhances the proliferation and migration of cancer cells." (PMID 32974137, 2020). "Anti-cancer chemotherapeutic agents such as gemcitabine and 5-fluorouracil, induced activation of the NLRP3 inflammasome, which was dependent on lysosomal permeabilization and the release of cathepsin B, while this activation in myeloid-derived suppressor cells blunted their anticancer efficacy." (PMID 33603747, 2020). "Immunogenic reprogramming of innate and adaptive immunity within the TME has brought to light the importance of NLRP3 signaling in primary tumors or innate immune cells in mediating immune evasion that not only promotes cancer dissemination but also allows clonogenic survival." (PMID 33613533, 2020). "Moreover, it raises the importance of Cathepsin B and the interest to develop inhibitor peptides targeting its interaction with NLRP3, an early and common event, to inhibit IL-1β production in inflammatory diseases or cancer." (PMID 32328491, 2020). "Moreover, in cancer patients diagnosed with painful neuropathy as a side effect of the drug Bortezomib, NLRP3 has been found to be overexpressed as a consequence of acetylation of histone H3 and H4 in the NLRP3 promoter region, thus driving the disease." (PMID 32883606, 2020). "In addition, the NLRP3 inflammasome has been observed to sustain cancer progression and lymph node metastasis in NSCLC patients by reducing E-cadherin and increasing Snail through IL-1β secretion." (PMID 33014808, 2020). "Several researchers report the effects of nutraceuticals, mainly polyphenols, on cancer, as well as the capacity of some flavonoids to suppress the NLRP3 inflammasome; however, studies regarding the relationship between nutraceuticals, NLRP3 inflammasome and cancer are still scarce." (PMID 32650482, 2020). "Moreover, NLRP3 downstream, IL-1β, also stimulates the production of ROS that, in turn, induces DNA damage and cancer development in CRC." (PMID 33613533, 2020).
cancer (continued). "However, altered expression of NLRP3 was found in several pathological conditions, including cancer." (PMID 33613529, 2020). "Silibinin, an anti-cancer agent used in breast cancer patients, has been shown to suppress cancer cell migration and invasion by interfering with ROS generation and suppressing NLRP3 inflammasome activation." (PMID 32703253, 2020). "In summary, targeting the NLRP3 inflammasome or its downstream pathways, either solely or in combination with chemotherapy or other immunotherapeutic approaches, hold a promising potential in cancers." (PMID 32733479, 2020). "Accordingly, this review aims to decode the complexity of NLRP3, whereby summarizing and clustering findings into cancer hallmarks and tissue contexts may expedite consensus and underscore the potential of the inflammasome in drug translation." (PMID 33613533, 2020). "Therefore, the activation of caspase-1 plays an important role in inhibiting the proliferation of cancer cells, and the compounds with an activating NLRP3 inflammasome effect have the potential to be the treatments for NSCLC." (PMID 31941010, 2020). "Other compounds include Andrographolide and Parthenolide, which mainly target NF-κB signaling pathway, but the later was also shown to directly inhibit NLRP3 inflammasome by interfering with its ATPase activity, have also shown promising results in several cancers." (PMID 32733479, 2020). "In addition to NLRP3’s implications in cancer progression through inflammatory pathways, it is worth mentioning other roles of this inflammasome in cancer pathogenesis." (PMID 32604771, 2020). "Therefore, to activate NLRP3 we treated all cancer cells and fibroblasts with LPS, followed by Nigericin." (PMID 33613529, 2020). "The NLRP3 inflammasome controls the EMT program during cancer pathogenesis." (PMID 31492049, 2019). "In short, the OS and DFS results show that high NLRP3 inflammasome expression (NLRP3/IL-18/ IL-1β/ASC) in LSCC cancer tissues forecasts a poor outcome compared to low NLRP3 inflammasome expression (NLRP3/IL-18/IL-1β/ASC) in cancer tissues (P < 0.05)." (PMID 31312615, 2019). "While activation of pyroptosis provides powerful ammunition against many types of cancers, other researchers have reported that the NLRP3 inflammasome and IL-1β pathway promote cancer progression in animal and human breast cancer models and asbestos-induced malignant mesothelioma." (PMID 31156630, 2019). "In this study, we investigated whether the inhibition of NLRP3 inflammasome in macrophages resulted in the regulation of metastatic potential of cancer cells." (PMID 31439870, 2019). "The role of the NLRP3 inflammasome in cancer is controversial." (PMID 31731747, 2019). "Thus, polymorphism of NLRP3 inflammasome related genes showed strong relevance with malignant tumors, but the regulatory role of the SNP of NLRP3 inflammasome related genes in the ALL bone marrow microenvironment has not been reported until now." (PMID 31428046, 2019). "Furthermore, the role of NLRP3 inflammasome in cancer development and progression remains controversial and conflicting." (PMID 31156650, 2019). "The roles of NLRP3 in cancer occurrence and progression have been intensively studied." (PMID 31492049, 2019). "Since IL-1β is the major cytokine secreted upon NLRP3 inflammasome activation in macrophages, we investigated whether IL-1β would increase the metastatic potential of cancer cells." (PMID 31439870, 2019). "NLRP3 inflammasome expression may be associated with the occurrence of EMT, cancer stem cells self-renewal activation and the overexpression of IL-18, which is related to increases in myeloid-derived suppressor cells (MDSCs)." (PMID 31312615, 2019). "The suppression of NLRP3 inflammasome in immune cells could be a novel strategy for anti-cancer therapy by reducing IL-1β secretion." (PMID 31439870, 2019). "Therefore, targeting the NLRP3 inflammasome pathway has opened the door for novel strategy in cancer prevention and treatment." (PMID 31412862, 2019).
cancer (continued). "Next, we hypothesized that the pharmacological inhibitors of NLRP3 inflammasome would suppress metastatic potential of cancer cells." (PMID 31439870, 2019). "The balance between IL-1β and IL-18 may be cell-type, tissue, and context dependent, providing a possible explanation for the controversial role of the NLRP3 inflammasome in cancer." (PMID 31558756, 2019). "High expression levels of NLRP3 in microglia and the contribution of IL-1β in the development and progression of malignant tumors create new interesting directions for future cancer studies." (PMID 31231208, 2019). "Thus, specific inhibitors of the NLRP3 inflammasome hold considerable promise as novel therapeutic agents aimed at treating cancers." (PMID 31492049, 2019). "We investigated whether the suppression of NLRP3 inflammasome activation by celastrol in macrophages contributed to the blockade of migration and invasion of cancer cells." (PMID 31439870, 2019). "To investigate these problems, we evaluated the expression of NLRP3 in ccRCC cancer tissues." (PMID 30770793, 2019). "We further examined whether the activation of NLRP3 inflammasome in macrophages enhanced the invasive activity of cancer cells." (PMID 31439870, 2019). "At nine weeks, momordicoside G treatment resulted in not only mild lung tissue injury but also slight carcinoma lesions which were in line with the decreased M1-like macrophages (iNOS+ cells) and NLRP3 inflammasome and the increased levels of alveolar IL-10 and TGF-β1." (PMID 30984004, 2019). "Moreover, it has been observed that pro-inflammatory cytokines including IL1β and NLRP3 were significantly up-regulated in visceral adipose tissue versus subcutaneous adipose tissue in cancer patients." (PMID 30447690, 2018). "In AMs the activation of TLR4/NLRP3 inflammasome was found severely decreased, adding to the hypothesis of cancer mediated immunesuppression." (PMID 30365491, 2018). "Knockdown of NLRP3 decreased proliferation of cancer cells, invasion, and EMT in vitro." (PMID 29386037, 2018). "NLRP3 inflammasome plays important roles in the etiology of inflammation and cancers." (PMID 29312552, 2017). "However, the roles of NLRP3 inflammasome in the tumorigenesis and development of cancer stem cells (CSCs) of squamous cell carcinoma of the head and neck (SCCHN) remain ambiguous." (PMID 28865486, 2017). "Although NLRP3 inflammasome has been reported to eliminate malignant progenitor cells by programmed cell death, more recent studies have shown that NLRP3 inflammasome plays a role in promoting cancer." (PMID 29312552, 2017). "However, the NLRP3 staining between stromal vs. benign epithelial cells (p = 0.004), and stromal vs. cancer cells (p = 0.0006) appeared significantly different." (PMID 28663562, 2017). "Targeting NLRP3 inflammasome is expected as an important means of cancer therapy." (PMID 29312552, 2017). "Co-treatment of lentinan with paclitaxel, an anti-cancer drug, to A549 cells induces reactive oxygen species (ROS) production and thioredoxin-interacting protein (TXNIP) expression, which are tightly associated with NLRP3 inflammasome activation." (PMID 28465544, 2017). "In addition, IL-1β, produced mainly by activated NLRP3 inflammasome, can also increase tumorigenesis and promote the migration of cancer cells." (PMID 28938606, 2017). "Cumulative studies demonstrated that inflammasomes, including NLRP3, could be activated by microbial pathogens and cancer." (PMID 28865486, 2017). "Whether NLRP3 inflammasome has beneficial or detrimental effect on the carcinogenesis and development of cancer stem cells in SCCHN remains unknown." (PMID 28865486, 2017). "All these findings suggest the pro-tumorigenic role of NLRP3 in cancer development." (PMID 27206676, 2016). "In this context, it is logical to deduce that NLRP3 may play a duplex role in controlling cancer growth." (PMID 27206676, 2016).
cancer (continued). "Therefore, a much more comprehensive analysis of NLRP3 using conditional knockout models and pharmacological activators or inhibitors is needed to decode the precise effects of NLRP3 on cancer development in the future." (PMID 27206676, 2016). "NLRP3 inflammasome plays an important role in the development of many cancer types." (PMID 24587153, 2014). "Overt activation of the NLRP3 inflammasome has been demonstrated to elicit cancer progression." (PMID 25071785, 2014). "The NLRP3 inflammasome, a protein complex controlling maturation of important pro-inflammatory cytokines interleukin (IL)-1β and IL-18, is also involved in tumorigenesis and metastasis of various cancers." (PMID 24223129, 2013). "NLRP3 activation by mitochondria-associated factors from cancer cells is not well studied and is an area that warrants further investigation." (PMID 24273542, 2013). "Moreover, phagocytosis of human cancer cells dying through autophagy was shown to trigger NLRP3 inflammasome activation and maturation of IL-1β in human macrophages via an ATP-dependent mechanism." (PMID 23316199, 2012). "In addition, NLRP3 inflammasome plays a crucial role in cancer and metabolic diseases." (PMID 41560727, 2025). "This divergence may reflect structural differences influencing enzyme binding, as verbascoside and related PEs have recently been shown to interact with NF-κB and NLRP3 inflammasome targets, suggesting that their role in inflammation-related cancer pathways may be broader than previously recognized." (PMID 41225814, 2025). "Thus, targeting the NLRP3 inflammasome presents a multifaceted approach to therapy that could address not only chronic inflammatory diseases but also cancer and drug toxicity." (PMID 40205269, 2025). "It was because that LPS could play a role in the cell pyroptosis, which has a close relationship with acute lung injury, therefore LPS is investigated as a therapy of cancer with its inhibition of cellular proliferation and apoptosis promotion through the caspase-11/NLRP3 inflammasome pathway." (PMID 39439897, 2024). "NLRP3 inflammasome is composed of NLRP3, apoptosis-associated speck-like protein containing CARD (ASC) and effector pro-caspase-1, and can affect the occurrence and development of IBD and even cancer via regulating the maturation, secretion, and pyroptosis of IL-1β and IL-18." (PMID 38650627, 2024). "However, the effect of preventing NLRP3-induced proinflammatory cytokine secretion by inhibiting the upstream signals and blocking the formation of the inflammasome complex assembly on cancer cell growth remains unknown." (PMID 38543085, 2024). "Hence, NLRP3 inflammasome exhibits contrasting roles in cancer development." (PMID 38649928, 2024). "Therefore, it is possible to characterize the NLRP3 inflammasome as a double-edged weapon for cancer, in that it may either inhibit the development of specific forms of cancer or, conversely, promote their occurrence." (PMID 38892354, 2024). "In this review article, we discuss the role of NLRP3 inflammasome-mediated inflammatory response in the pathophysiology of various cancer types; understanding this role is essential for the development of innovative therapeutic strategies for cancer growth and spread." (PMID 39769450, 2024). "In addition, NLRP3 expression in cancer cells could differ depending on their intrinsic proinflammatory cytokines’ secretion capacity without the need for a priming stimulus, such as LPS." (PMID 38543085, 2024). "Key questions include whether NLRP3 inflammasome activation promotes cancer progression, its specific impact on various cancers, and the mechanisms through which inhibiting NLRP3 inflammasome activation mediates cancer progression—all warranting further exploration." (PMID 38317229, 2024). "However, there are also circumstances in which a chronic activation of NLRP3 speck is deleterious and might, at least partially, subtend the development of GI-associated disorders, such as IBD or cancer." (PMID 37891577, 2023).
cancer (continued). "However, there is a limited understanding of the interaction between NLRP3 activation and hormone receptor inhibition in cancer cells, which could contribute to the therapeutic efficacy of these drugs." (PMID 36902278, 2023). "Also, several GPCRs have been reported to be involved in the activation and regulation of the NLRP3 inflammasome by sensing multiple ions, metabolites, neurotransmitters and other therapeutic applications, including cancer, on similar molecules related to analgesic and anti-inflammatory drugs." (PMID 38004449, 2023). "In addition, NLRP3 was found to be overexpressed in PBMCs of various cancer patients." (PMID 37762557, 2023). "Whether NLRP3 exerts functions unrelated to immunity in cancer remains unexplored." (PMID 36746533, 2023). "The well-studied NLRP3 (NLR family pyrin domain-containing 3) inflammasome plays a dominant role in inducing pyroptosis and promoting inflammation, acting as an essential regulator of immune response that can be activated by chemotherapy or radiation treatment in various cancers, including NSCLC." (PMID 35379783, 2022). "Similarly, a recent study reported attenuation of diastolic dysfunction in a diabetic model with nutraceuticals like quercetin and boswellic acid through NLRP3 inflammasome and cytokines, which showed a potential effect against cancer cell survival and chemoresistance." (PMID 36068525, 2022). "Therefore, the Az’s effect on NLRP3 expression in cancer cells could vary depending on the degree of mitochondrial damage inflicted by this antibiotic." (PMID 36012769, 2022). "Thus, NLRP3 plays different roles in various types of cancer." (PMID 35664308, 2022). "Therefore, we suggest that Cf could suppress NLRP3 in cancer cells when LPS is used as a priming agent." (PMID 36012769, 2022). "Thus, the NLRP3 inflammasome and its components can be targeted to reduce the effect of cancers." (PMID 35877745, 2022). "Thus, inhibiting NLRP3 inflammasome activation may suppress cancer cell proliferation and metastasis in NSCLC." (PMID 36118863, 2022). "In some cancers, the NLRP3 inflammasome may have a protective role." (PMID 36555392, 2022). "Thus, NLRP3 is a therapeutic target to reverse canonical STAT3 mediated cancer promotion." (PMID 34531850, 2021). "However, in cancer, this fine balance between NLRP3 activation, inflammation and autophagy might be dysregulated to support cell proliferation, survival and resistance to chemotherapy of malignant cells in an adaptive and context-dependent fashion." (PMID 33525345, 2021). "In addition, with a current hypothesis, further studies are needed to validate the precise mechanism of exosome-mediated-NLRP3 inflammasome activities in cancer progression." (PMID 35047512, 2021). "As a member of the inflammasome family, NOD-like receptor family pyrin domain containing 3 (NLRP3) is the most studied and best characterized inflammasome, and has been shown to be involved in several pathologies, including neurodegenerative diseases, atherosclerosis, and cancer." (PMID 34681768, 2021). "Therefore, targeting the NLRP3 inflammasome could be an approach to overcome pro-tumorigenic inflammation and provide an option for the development of novel therapeutics for cancer treatment." (PMID 34577552, 2021). "Thus, we analyzed whether MNS could affect the metastatic behaviors of cancer cells through NLRP3 inflammasome inhibition." (PMID 32974137, 2020). "Similarly, treatment with MCC950 attenuated mechanical allodynia in a rodent model of cancer-induced bone pain, and in oxaliplatin-induced peripheral neuropathy model and restored the increased expression levels of NLRP3, ASC, caspase-1 and IL-1β in spinal cord to basal levels." (PMID 32973552, 2020). "Indeed, NLRP3 inflammasome plays a key regulatory role in inflammation-induced cancer." (PMID 33603669, 2020).